NEDD4 (NEDD4 E3 ubiquitin protein ligase)
Diseases named in the same sentence as NEDD4 in open-access papers (continued):
Sharing a sentence is not in itself a finding about the gene and the disease.
breast cancer (continued). "In another study of primary breast cancer, NEDD4-1 expression were not significantly related with clinical outcomes of HER2-amplified breast cancer." (PMID 37291499, 2023). "Another research group reported that the prognosis of HR-positive breast cancer was independent of the expression level of NEDD4, while the prognosis of HR-negative breast cancer was dependent on that level." (PMID 36672488, 2023). "In contrast, a previous study revealed that a low expression of NEDD4 did not affect the clinical prognosis of patients with breast cancer." (PMID 36672488, 2023). "In keeping with this finding, we examined a panel of breast cancer cell lines, and found that the expression of Nedd4l, but not Nedd4, a close member of Nedd4l, seemed like to negatively correlate with AKT phosphorylation, especially with AKT‐pT308." (PMID 34278744, 2021). "Our results suggest that NEDD4 is not responsible for the frequent down-regulation of the PTEN protein in human breast carcinoma." (PMID 26276352, 2016). "To this end, we retro-virally expressed a non-degradable mutant form of NEDD4 (NEDD4-S347A/S348A, referred to as NEDD4-AA) or wild-type NEDD4 (NEDD4-WT) in the breast cancer cell line MDA-MB-231 and the prostate cancer cell line DU145." (PMID 24657926, 2014). "However, contrary reports showed that NEDD4 is not involved in PTEN degradation in breast cancer and mouse embryonic fibroblast cells." (PMID 36672488, 2023). "Besides, a combination treatment by NEDD4-1 and WWP1 inducers for melanoma cancer, NEDD4-1 and ITCH inhibitors for prostate cancer, NEDD4-1 and SMURF1 for the HCC, as well as SMURF2 inducers and ITCH inhibitors for the breast cancer can be considered as the effective therapeutic approaches." (PMID 36918822, 2023). "However, subsequent studies have shown that there is no such correlation in breast cancer, and NEDD4 promote cancer cell growth by facilitating the activation of Akt." (PMID 34298639, 2021). "Kaplan–Meier curves showed that the NEDD4 level was not a prognostic indicator for DFS and OS in the HR-negative breast cancer patients." (PMID 36672488, 2023). "NEDD4 and its potential role in PTEN regulation in breast cancer have not been studied." (PMID 26276352, 2016).
lung carcinoma (27 papers, 2014 to 2025). "It was reported that NEDD4 is linked with the progression of lung cancer and is overexpressed in a considerable proportion of NSCLC patients concerning chemosensitivity and prognosis." (PMID 36293239, 2022). "It was also shown that NEDD4 is important for lung cancer metastasis by increasing cathepsin B secretion or causing PTEN degradation." (PMID 36293239, 2022). "Our studies propose a novel mechanism underlying the EGFR-promoted lung cancer cell migration that is mediated by NEDD4 through regulation of cathepsin B secretion." (PMID 29455656, 2018). "Our studies have provided a new vision to the mechanism underlying the NEDD4-mediated lung cancer cell migration." (PMID 29455656, 2018). "NEDD4 promoted the K48-linked ubiquitination of HMGCL in lung cancer cells." (PMID 36923932, 2023). "Another study reported that NEDD4 is closely linked to the development and progression of lung cancer due to its overexpression in a significant fraction of NSCLC, promotion of PTEN degradation, and enhancement of the malignant characteristics of lung epithelial cells." (PMID 36293239, 2022). "Furthermore, we examined the role of NEDD4 in lung cancer H1650 cells that contain an EGFR deletion mutation, which is a common mutation that drives tumorigenesis and progression in lung cancer patients." (PMID 29455656, 2018). "To further investigate the mechanism underlying the effect of NEDD4 on EGF-stimulated lung cancer cell migration, we first examined whether NEDD4 is in the EGFR signaling complex." (PMID 29455656, 2018). "The findings of this study uncover the novel functions of NEDD4 in the ketone body metabolism, and further indicated the tumor-promoting effects of NEDD4 in lung cancer." (PMID 36923932, 2023). "Previous studies have shown that NEDD4 promotes the progression of lung cancer through multiple mechanisms 34-36." (PMID 36923932, 2023). "On the other hand, VPS34 depletion in lung cancer cells was found to not only impair the activity of NEDD4-1 to stabilize Beclin-1, but also cause NEDD4-1-mediated proteasomal degradation of Beclin-1 via K11-linked ubiquitination." (PMID 36918822, 2023). "It was also reported that in lung cancer and hepatocellular carcinoma, NEDD4 promotes cancer progression by negatively regulating PTEN." (PMID 36774408, 2023). "Research reports have indicated that NEDD4 is expressed in many tumor types, such as gastric cancer, lung cancer, and colorectal cancer." (PMID 35861040, 2023). "Our findings in this study also uncover the novel mechanism through which NEDD4 promotes lung cancer." (PMID 36923932, 2023). "NEDD4-1 has been found to induce autophagy and proliferation in the prostate, HCC, neuroblastoma, and lung cancer cells, suggesting that NEDD4-1 inhibition is a suitable therapeutic strategy for treating these cancer cells." (PMID 36918822, 2023). "Through stimulation of the lysosomal cathepsin B secretion pathway, NEDD4 can also mediate EGFR cell migration signaling in lung cancer cell lines." (PMID 36293239, 2022). "We subsequently examined the effect of MEKK5 overexpression on the NEDD4-mediated lung cancer cell migration signaling." (PMID 34833029, 2021). "In line with our previous studies, we observed that overexpression of MEKK5 impaired NEDD4-dependent cell migration capacity in lung cancer A549 cells." (PMID 34833029, 2021). "In lung cancer, NEDD4-1 as E3 ligase handles PTEN stability and gives a mechanism that contributes to the inactivation of the PTEN gene." (PMID 34769401, 2021). "We showed previously that either knockdown of NEDD4 or overexpression of MEKK5 significantly reduces lung cancer cell migration." (PMID 34833029, 2021). "RNF128 can also bind other E3 ubiquitin ligases, such as NEDD4, to promote the migration of lung cancer cells." (PMID 33962392, 2021).
lung carcinoma (continued). "Upregulation of NEDD4 mediates cell migration in lung cancer cells, while downregulation of NEDD4 inhibits cell growth and invasion, and induces cell apoptosis in bladder cancer cells." (PMID 33875644, 2021). "Our results demonstrated that NC possessed anticancer activity via suppression of NEDD4 in lung cancer." (PMID 33288736, 2020). "In support of these data, we observed that NEDD4 upregulation reduced the apoptotic death of lung cancer cells." (PMID 33288736, 2020). "Consistently, combination treatments of the lung cancer cells led to a higher suppression of cell migration and invasion than NC treatment alone or NEDD4 downregulation alone." (PMID 33288736, 2020). "Our MTT data demonstrated that NEDD4 overexpression promoted cell viability in H1299 and H460 lung cancer cells." (PMID 33288736, 2020). "One group reported that NEDD4 knockdown reduced proliferation, migration and invasion in A549 lung cancer cells via targeting phosphatase and tensin homolog (PTEN) and the phosphatidylinositol 3-kinase (PI3K)/Akt pathway." (PMID 33288736, 2020). "The NC and NEDD4 siRNA combinations led to a greater reduction in cell viability of lung cancer cells than that after single treatment." (PMID 33288736, 2020). "To define the potential role of NEDD4 in NC-involved antitumor activity in lung cancer, we decreased NEDD4 expression using NEDD4 siRNA transfection and cotreated the H1299 and H460 cells with NC." (PMID 33288736, 2020). "The migration of lung cancer cells after NEDD4 cDNA transfection plus NC exposure was also evaluated by Transwell chamber migration assay." (PMID 33288736, 2020). "NEDD4-1 is overexpressed in multiple types of human cancers, such as gastric, colorectal, breast and lung cancers, and inhibition of NEDD4-1 can result in significant reduction of tumor growth." (PMID 31756921, 2019). "NEDD4 mediates the EGFR lung cancer cell migration signaling through promoting lysosomal secretion of cathepsin B." (PMID 29455656, 2018). "Taken together, we conclude that it is unlikely for NEDD4 to promote lung cancer cell migration through ubiquitination and down-regulation of PTEN." (PMID 29455656, 2018). "This study is to elucidate the mechanism by which NEDD4 mediates the EGFR lung cancer migration signaling." (PMID 29455656, 2018). "In this research article, we demonstrated that NEDD4 interacts with EGFR upon EGF stimulation in lung cancer cells." (PMID 29455656, 2018). "Further studies on these pathways in future are necessary for elucidation of the mechanism by which NEDD4 promotes secretion of cathepsin B and the lung cancer cell migration." (PMID 29455656, 2018). "Taken together, our data have demonstrated that NEDD4 is a key E3 ubiquitin ligase mediating the EGFR cell migration signaling in lung cancer cells." (PMID 29455656, 2018). "Lentiviral vector-loaded NEDD4 shRNA was used to deplete endogenous NEDD4 in lung cancer cell lines." (PMID 29455656, 2018). "In this proposed pathway, the NEDD4-dependent secretion of the lysosomal cathepsin B is a key step for lung cancer cell migration." (PMID 29455656, 2018). "Effects of the NEDD4 knockdown on the EGFR-dependent or independent lung cancer cell migration were determined using the wound-healing and transwell assays." (PMID 29455656, 2018). "NEDD4 was co-immunoprecipitated with EGFR upon EGF stimulation in both A549 and H358 cells, suggesting that NEDD4 specifically interacts with activated EGFR in lung cancer cells." (PMID 29455656, 2018). "We wonder if the role of NEDD4 in endosomal trafficking is relevant to the EGFR-promoted lung cancer cell migration." (PMID 29455656, 2018). "NEDD4 over-expression augmented the tumorigenicity of lung cancer cells, while the PTEN gene product remained intact." (PMID 28423617, 2017). "Taken together, these results indicated that by reducing endogenous SAG level, NEDD4-1 overexpression sensitized lung cancer cells to etoposide-induced growth suppression by enhancing apoptosis." (PMID 25216516, 2014).
lung carcinoma (continued). "Second, the protein levels of SAG in multiple human lung cancer cell lines are inversely correlated with the levels of NEDD4-1." (PMID 25216516, 2014). "We further transfected NEDD4-1 into H358 lung cancer cells, which show a low level of NEDD4-1 and a high level of SAG, and found a dose dependent reduction of endogenous SAG." (PMID 25216516, 2014). "Nedd4 was found to be involved in ferroptosis along with VDAC2 in lung cancer." (PMID 38634270, 2024). "In addition, mutation of Ser258 to alanine inhibited the ubiquitination of HMGCL by NEDD4 and thus inhibited the anchorage-independent growth of lung cancer cells more efficiently than did wild-type HMGCL." (PMID 36923932, 2023). "NEDD4 is essential for EGF-induced migration of lung cancer cells." (PMID 36923932, 2023). "Binding of HMGCL to NEDD4 might weaken the interaction between NEDD4 and these oncogenes, thus stabilizing these oncogenes and promoting the progression of lung cancer." (PMID 36923932, 2023). "A study on lung cancer proved that upregulation of NEDD4 via the PI3K/Akt pathway might contribute to tumor growth and modulate lung ADC chemoresistance." (PMID 36293239, 2022). "NEDD4 was confirmed to mediate cell migration signaling of EGFR in lung cancer." (PMID 35090513, 2022). "NEDD4 overexpression accelerates lung cancer cell proliferation, migration, and drug resistance." (PMID 35646490, 2022). "NEDD4 has also proved its oncogenic activity via EGFR in lung cancer cell lines." (PMID 34769401, 2021). "Furthermore, overexpression of MEKK5 significantly reduced the NEDD4-promoted lung cancer cell migration." (PMID 34833029, 2021). "Furthermore, we found that NEDD4 promotes lung cancer cell migration by facilitating the EGFR-dependent lysosomal secretion of cathepsin B." (PMID 34833029, 2021). "Finally, NEDD4 inhibition attenuated the migratory and invasive abilities ofH1299 and H460 lung cancer cells." (PMID 33288736, 2020). "Importantly, NEDD4 upregulation the abrogated NC-triggered induction of cell apoptosis in H1299 and H460 lung cancer cells." (PMID 33288736, 2020). "Moreover, overexpression of NEDD4 neutralized the reduction in cell viability induced by NC exposure in lung cancer cells." (PMID 33288736, 2020). "Thus, NC conducted antitumor effects in lung cancer cells in part via attenuation of NEDD4 expression." (PMID 33288736, 2020). "NEDD4 modulation was evaluated by western blotting assays of lung cancer cells after NC treatments." (PMID 33288736, 2020). "Notably, upregulation of NEDD4 abolished the NC-induced retardation of cell migration in lung cancer cells." (PMID 33288736, 2020). "Next, we assessed whether increased NEDD4 abolished the NC-triggered suppression of cell viability in lung cancer cells." (PMID 33288736, 2020). "Overexpression of NEDD4 reversed the NC-involved reduction in cell invasion in lung cancer." (PMID 33288736, 2020). "Furthermore, our rescue experiments dissected that overexpression of NEDD4 abrogated the NC-mediated antineoplastic effects in lung cancer cells." (PMID 33288736, 2020). "Similarly, NEDD4 suppression by siRNA transfection stimulated the apoptosis of H1299 and H460 lung cancer cells." (PMID 33288736, 2020). "Here, we reported that NC suppressed the expression of NEDD4 in lung cancer cells." (PMID 33288736, 2020). "We explored whether NC performed cell viability inhibition via downregulation of NEDD4 in lung cancer cells." (PMID 33288736, 2020). "NEDD4 overexpression was detected in malignant gastric, colorectal, and lung cancer cells." (PMID 31856858, 2019). "NEDD4 is required for the EGF-promoted lung cancer cell migration." (PMID 29455656, 2018). "Thus, it is likely that NEDD4 mediates the EGFR cell migration signaling in lung cancer cell lines through activation of the lysosomal cathepsin B secretion pathway." (PMID 29455656, 2018). "Knockdown of NEDD4 significantly reduces EGFR-promoted lung cancer cell migration rate." (PMID 29455656, 2018).
lung carcinoma (continued). "Similarly, suppression of NEDD4 expression significantly inhibited proliferation of NSCLC cells in vitro and tumor growth in vivo, whereas NEDD4 overexpression augmented the tumorigenicity of lung cancer cells with an intact PTEN gene." (PMID 24657926, 2014). "However, NEDD4-2 has more complex functions than NEDD4 as it inhibits lung cancer cell metastasis; on the other hand, it enhances lung cancer survival by causing general control nonderepressible 2 (GCN2) degradation." (PMID 36293239, 2022). "Furthermore, overexpression of MEKK5 inhibits the NEDD4-mediated lung cancer cell migration." (PMID 34833029, 2021). "To evaluate whether the antitumor effects of NC are mediated via regulation of NEDD4, we transfected a cDNA plasmid into lung cancer cells to increase the NEDD4 level and detected whether upregulation of NEDD4 could reverse the anticancer effect of NC on lung cancer cells." (PMID 33288736, 2020). "Therefore, we tested whether NC inhibited NEDD4 expression and led to suppression of migration and invasion of lung cancer cells." (PMID 33288736, 2020). "Indeed, this hypothesis is further supported by previous studies that showed high NEDD4 expression promoted tumor progression in lung cancer and gastric cardia adenocarcinoma." (PMID 31856858, 2019). "Compared with the healthy people, in the plasma of lung cancer patients, only the expression of KLHL3 was continuously downregulated, while NEDD4 and UBAC1 were increased." (PMID 35313857, 2022). "Our previous studies have shown that the HECT E3 ubiquitin ligase NEDD4 and kinase MEKK5 both play an essential role in lung cancer migration." (PMID 34833029, 2021). "To investigate the biological role of the interaction of MEKK5 with NEDD4, we first made a stable NEDD4 and MEKK5 overexpression cell line in lung cancer A549 cells separately and carried out a transwell assay." (PMID 34833029, 2021). "More importantly, overexpression of MEKK5 produced an opposite effect on cell migration to that of NEDD4, pointing to an important role of MEKK5 in negatively regulating lung cancer cell migration, probably through inhibiting the NEDD4 ligase activity." (PMID 34833029, 2021). "Therefore, inactivation of NEDD4 might be a useful strategy for lung cancer therapy." (PMID 33288736, 2020). "Consistent with the role of NEDD4, cathepsin B is pivotal for both basal and the EGF-stimulated lung cancer cell migration." (PMID 29455656, 2018). "More importantly, NEDD4 mediates both the EGFR-dependent and -independent secretion of lysosomal cathepsin B, which in turn promotes lung cancer cell migration." (PMID 29455656, 2018). "In this report, we found that NEDD4 interacts with EGFR and participates in both the basal and the EGFR-signaling-dependent lung cancer cell migration." (PMID 29455656, 2018). "However, how NEDD4 promotes the EGFR-dependent lung cancer cell migration is unknown." (PMID 29455656, 2018). "Our data suggest that the interaction between NEDD4 and MEKK5 efficiently inhibits the NEDD4 migration signaling, which may provide a new strategy for the antimetastatic therapy of lung cancer." (PMID 34833029, 2021). "Furthermore, the E3 ubiquitin ligase NEDD4 interacted with EGFR, which mediated lung cancer cell migration through activating CTSB." (PMID 32331211, 2020). "The NEDD4-mediated EGFR migration signaling is not dependent on the PTEN/PI3K/AKT pathway in lung cancer cells." (PMID 29455656, 2018). "Furthermore, knockdown of NEDD4 inhibits EGF-dependent unconventional lysosomal cathepsin B secretion, which is an important cellular process for lung cancer cell migration." (PMID 29455656, 2018). "Consistent with our previous observation that SAG silencing sensitized cancer cells to etoposide-induced cell killing, NEDD4-1 overexpression, which reduces SAG level, also sensitized lung cancer cells to etoposide-induced growth suppression via apoptosis induction." (PMID 25216516, 2014).
lung carcinoma (continued). "Moreover, endogenous NEDD4 and HMGCL bound to each other in lung cancer cells." (PMID 36923932, 2023). "Moreover, NEDD4 suppression attenuated the cell proliferation of NSCLC cells, while overexpression of NEDD4 promoted cell growth in nontransformed lung epithelial cells and lung cancer cells." (PMID 33288736, 2020). "To connect the NEDD4-mediated lung cancer cell migration, including both the EGF and the non-EGF dependent lung cancer cell migration, to lysosomal secretion, we examined the effect of CA-074Me, a specific inhibitor of cathepsin B, on lung cancer A549 cell migration using a wound healing assay." (PMID 29455656, 2018). "To confirm the role of NEDD4 in lysosomal secretion, we detected the secreted lysosomal protease cathepsin B in culture medium using an ELISA assay in both the vector control and the shNEDD4 lung cancer A549 cells with or without EGF stimulation." (PMID 29455656, 2018). "We first determined potential correlation in the protein levels between SAG and NEDD4-1 in multiple human lung cancer cell lines, and found that the level of SAG, but not its family member RBX1, is largely correlated in a inverse manner with NEDD4-1." (PMID 25216516, 2014).